NRXN2 (neurexin 2)
Diseases named in the same sentence as NRXN2 in open-access papers:
NRXN2 is named in the same sentence as 43 diseases in open-access papers, as found by Europe PMC text mining. Sharing a sentence is not in itself a finding about the gene and the disease. The quoted sentences say what the papers report.
autism (10 papers, 2015 to 2022). Persistent deficits in social interaction and communication and interaction as well as a markedly restricted repertoire of activity and interest as well as repetitive patterns of behavior. "Neurexin performs distinct regulatory functions in different classes of neurons, and any mutation or deletion of Neurexin (NRXN1 and NRXN2) genes have been associated with autism-associated behavioral changes in experimental mice." (PMID 34833061, 2021). "In several cases, it is likely that the SVs discovered are causative variants due to their disruptive nature on protein-coding gene sequence potential, including the ablation of the key synaptic protein neurexin-2, which caused autism-related behaviours when induced experimentally in mice." (PMID 33056985, 2020). "These included the regions harboring known autism risk genes, CSMD1, NRXN2, and RBFOX1, all of which were found to be hypomethylated in both discovery and validation analyses." (PMID 36035158, 2022). "In the current study, a dual-luciferase reporter assay confirmed miR-873 variants have a 20-30% inhibition/dysregulation effect on candidate autism risk genes ARID1B, SHANK3 and NRXN2 and also confirmed the affected expression with qPCR." (PMID 33262327, 2020). "Autism risk genes, ARID1B, SHANK3 and NRXN2 were specially of interst, using a dual-luciferase assay we confirmed the direct targeting of MRE of SHANK3 by miR-873 albeit, WT and Mut miR-873 mimics similarly dysregulate Renilla luciferase." (PMID 33262327, 2020).
Anxiety (8 papers, 2014 to 2023). Intense feelings of nervousness, tension, or panic often arise in response to interpersonal stresses. "The impact of a constitutive deletion of Nrxn2 gene on associated symptoms of ASD including anxiety behavior and cognitive behaviors has also been investigated." (PMID 36923655, 2023). "Among them, some differentially expressed proteins have been reported to involve in anxiety and depression-like behavior, such as Nrxn2 and 5-HT1A." (PMID 31440134, 2019). "We next analyzed the effects of Nrxn2 deletion on anxiety and cognitive behaviors." (PMID 36941261, 2023). "Therefore, when not influenced by a strong anxiogenic phenotype, Nrxn2α HET mice show a subtle impairment in social tasks, potentially confirming Nrxn2 deletion as causing changes in social motivation that is not solely driven by their heightened anxiety." (PMID 26595880, 2015).
schizophrenia (7 papers, 2015 to 2024). A major psychotic disorder characterized by abnormalities in the perception or expression of reality. "Genomic alterations in NRXN genes (NRXN1, NRXN2, and NRXN3) are associated with neuropsychiatric disorders, including autism spectrum disorders and schizophrenia." (PMID 39518976, 2024). "The mutations of the NRXN2 gene were displayed in ASD, schizophrenia, ID, and other several neuropsychiatric disorders." (PMID 34777568, 2021). "Mutations in NRXN1, NRXN2, NLGN2, NLGN4, and SHANK3 genes related to ASD have been also found in schizophrenia patients." (PMID 25780553, 2015). "Some of the mutations of the genes related to ASD, including NRXN1, NRXN2, NLGN2, NLGN4, SHANK3, and SynGAP, have been also found in the schizophrenia patients; for instance, two de novo mutations (R1117X and R536W) were identified in the SHANK3 gene of two families of schizophrenia." (PMID 25780553, 2015).
autism spectrum disorder (6 papers, 2015 to 2025). A spectrum of developmental disorders that includes autism, and Asperger syndrome. "Human genetic studies have found heterozygous deletions affecting NRXN1 and NRXN2, encoding α-neurexin I (Nrxn1α) and α-neurexin II (Nrxn2α), in individuals with autism spectrum disorders and schizophrenia." (PMID 26595880, 2015). "Importantly, Nrxn1 and Nrxn2, along with the Nrxn3, belong to the neurexin gene family, which has been linked to autism spectrum disorder (ASD), and epilepsy." (PMID 40608247, 2025). "In addition, given the high implication of Nrxn2 and JNKs in neurodevelopmental disorders such as autism spectrum disorders, it will be very important to gain more insights into the relationship between JNK signaling and Nrxns." (PMID 38571813, 2024).
Cognitive impairment (3 papers, 2014 to 2022). Abnormal cognition is characterized by deficits in thinking, reasoning, or remembering. "We identified and positively validated five novel proteins (NCAM2, NPTXR, NRXN2, RELN, and CNTN2) as promising biomarkers for cognitive impairment following aSAH." (PMID 35602555, 2022).
epilepsy (3 papers, 2023 to 2025). A brain disorder characterized by episodes of abnormally increased neuronal discharge resulting in transient episodes of sensory or motor neurological dysfunction, or psychic dysfunction. "The high susceptibility of Nrxn2 cKO mice to spontaneously recurring seizures is a critical piece of information since epilepsy has been diagnosed in 9-19% of ASD patients." (PMID 36941261, 2023). "Increased network excitability in vitro could indicate an increased risk for epilepsy in vivo, a phenotype observed in humans with NRXN2 mutations." (PMID 36941261, 2023). "Considering that 14% of all NRXN2 mutations reported have resulted in both ASD and ASD-associated disorders, the Nrxn2 cKO mouse model is a valuable genetic tool to study biological pathways underlying the co-morbidity of ASD with epilepsy and other neurodevelopmental disorders." (PMID 36941261, 2023). "Recent studies identified NRXN2 mutations in ASD and epilepsy, but little is known about Nrxn2’s role in a circuit-specific manner." (PMID 36941261, 2023). "To test for spontaneous electrographic seizures, the hallmark of epilepsy, we performed 2–4 weeks of continuous (24 h/day) video-EEG monitoring in WT and Nrxn2 cKO mice." (PMID 36941261, 2023). "Here, we conditionally deleted Nrxn2 under the Emx1Cre promoter which is predominately expressed in excitatory neurons of neocortex and hippocampus regions that are heavily implicated in ASD and epilepsy." (PMID 36941261, 2023). "Genetic truncations and variations in NRXN2 have been reported in human patients diagnosed with neuropsychiatric disorders including autism spectrum disorder (ASD) and epilepsy." (PMID 36941261, 2023).
gout (3 papers, 2017 to 2023). A condition characterized by painful swelling of the joints, which is caused by deposition of urate crystals. "The SNPs rs55975541 in CDC42BPG, and rs11231825/rs9734313 in SLC22A12/NRXN2, and rs10897526 in MAP4K2 on chromosome 4 were previously reported to be associated with hyperuricemia or gout." (PMID 29558500, 2018). "Interestingly, three genes (PDZK1, GCKR and HNF4G) associated with urate influenced the risk of gout, but the other five genes (TCF7L2, LRRC16A, ESR1, NRXN2 and ALPK1) did not, suggesting that elevated serum urate concentration is necessary but not sufficient for the pathogenesis of gout." (PMID 28252667, 2017).
Alzheimer disease (2 papers, 2018 to 2021). A progressive, neurodegenerative disease characterized by loss of function and death of nerve cells in several areas of the brain leading to loss of cognitive function such as memory and language. "NRXN2 was reported to modulate NLRP3 in AD brain regions to affect Alzheimer's disease." (PMID 34777568, 2021).
depression (2 papers, 2018 to 2019). "Downregulation of synaptic genes like Syn1, Rab3a, Camk2a, Nrxn2 have been strongly associated with major depression." (PMID 29743870, 2018).
medulloblastoma (2 papers, 2020 to 2021). A malignant, invasive embryonal neoplasm arising from the cerebellum. "One study identifies NRXN2 as a reliable predictor of overall survival in medulloblastoma, which is conducive to well understand medulloblastoma's pathogenesis and treatment in the future." (PMID 34777568, 2021).
Parkinson disease (2 papers, 2022 to 2024). A progressive degenerative disorder of the central nervous system characterized by loss of dopamine producing neurons in the substantia nigra and the presence of Lewy bodies in the substantia nigra and locus coeruleus. "NRXN2, involved in neuronal and synaptic functioning, is predominantly expressed in the substantia nigra, a region affected in Parkinson’s disease (PD), and is considered a potential PD biomarker." (PMID 39766348, 2024).
spinal muscular atrophy (2 papers, 2019 to 2023). A motor neuron disease that affect the muscles, and characterized by muscle weakness and atrophy resulting from progressive degeneration and irreversible loss of the anterior horn cells in the spinal cord (i.e., lower motor neurons) and the brain stem nuclei. "Changes in NRXN2 expression in motor neurons have been reported as the cause of spinal muscular atrophy in mammals." (PMID 30791866, 2019). "Nrxn2 is important at the pre-synaptic membrane levels since it is involved in the release of neurotransmitters, and it is one target in the clinical development of spinal muscular atrophy." (PMID 36983897, 2023).
Atrophy (1 paper, 2022). Any weakening or degeneration, especially through lack of use. "More generally, genetic aberrations of many of the differentially methylated genes in our study, i.e., TRIO, NRXN2, SYN2, CACNA1E, DNM1 and RAB11B, have been associated with movement disorders, cognitive and visual impairments and brain abnormalities (e.g., atrophy, white matter apoplasia)." (PMID 35094644, 2022).
brain tumor (1 paper, 2020). "However, NRXN2 expression was significantly lower in in CNS and brain tumor compared to normal tissues which was also consistent with our results." (PMID 33101383, 2020).
Hypertension (1 paper, 2022). The presence of chronic increased pressure in the systemic arterial system. "Rs3775948.GG of SLC2A9/GLUT9, rs504915.AA of NRXN2/URAT1, and 7 clinical features (age, hypertension, nephrolithiasis, blood glucose, serum urate, urea nitrogen, and creatinine) were generated by LASSO." (PMID 35264217, 2022).
hypogonadism (1 paper, 2024). A disorder characterized by decreased function of the gonads. "Our study was apparently the first to report decreased expression of the NRXN2 in DevF2 follicles at the expected time of deviation, a gene known to be involved in transmission of nerve signals and hypogonadism." (PMID 39468655, 2024).
memory impairment (1 paper, 2018). "A recent study in mice suggested that NRXN-2 interacts with Aβ oligomers, resulting in loss of synapses, whereas blocking of this interaction prevented Aβ-induced memory impairment." (PMID 29370833, 2018).
migraine (1 paper, 2021). "We have not found any statistically significant allelic or haplotypic associations between NRXN2 and migraine susceptibility." (PMID 34126933, 2021). "Tagging single nucleotide polymorphisms of NRXN2 were genotyped to assess the association between NRXN2 and migraine susceptibility." (PMID 34126933, 2021). "Our first aim was to assess association between NRXN2 SNPs and migraine susceptibility." (PMID 34126933, 2021). "This study unravels, for the first time, the gene-gene interactions between NRXN2, GABRE - a GABAA-receptor - and CASK, importantly it shows the synergetic effect between those genes and its relation with migraine susceptibility." (PMID 34126933, 2021). "In conclusion, we found a very significant (two-way) interaction in females between NRXN2-GABRE and NRXN2-CASK associated with migraine susceptibility." (PMID 34126933, 2021). "We found 2 strong synergistic interactions, demonstrated by both MDR software and logistic regression analyses, between migraine susceptibility and NRXN2-GABRE and NRXN2-CASK." (PMID 34126933, 2021). "We for the first time show that the genetic interaction and synergetic effect between variants in NRXN2, GABRE and CASK, affects migraine predisposition." (PMID 34126933, 2021). "Therefore, we aimed to further investigate the role and interaction of NRXN2, SYT1, GABRE and CASK, additional components involved in the control mechanisms of neurotransmitter release apparatus in migraine susceptibility." (PMID 34126933, 2021). "Likewise, we also verified the evidence for genetic interaction between NRXN2 and CASK in migraine susceptibility." (PMID 34126933, 2021). "The involvement of NRXN2 gene in migraine is reported for the first time in this study, allowing new hypotheses to be generated that can be translated into new GWA and functional studies to reveal the its underlying biological mechanisms." (PMID 34126933, 2021).
prion disease (1 paper, 2014). A transmissible disease that is caused by a protein that is able to induce abnormal folding of normal cellular proteins, leading to characteristic spongiform brain changes, which are associated with neuronal loss without an inflammatory response. "Four proteins (NRXN2, KLKB1, KARS, and LAMA3) that harbour rarely observed SNVs have biological interactions that are associated with prion diseases and/or prion protein." (PMID 25149502, 2014). "Four proteins (NRXN2, KLKB1, KARS, and LAMA3) that harbour rarely observed single-nucleotide variants showed biological interactions that are associated with prion diseases and/or prion protein in our biological network analysis." (PMID 25149502, 2014).
Sepsis (1 paper, 2019). Sepsis is defined as life-threatening organ dysfunction caused by a dysregulated host response to infection. "Previous research has described an increased expression of synaptic genes during the progression from normal aging to neurodegenerative disease, including genes we observed to increase in older males on day 4 of sepsis (Cacnb1, Cacna1a, Ephb4, Glul, Jph3, Mink1, Nrxn2, Grasp)." (PMID 31278440, 2019).
thyroid (1 paper, 2021). "Through KEGG, we analyzed the molecular function of NRXN2 in thyroid carcinogenesis." (PMID 34777568, 2021).
thyroid tumor (1 paper, 2021). A benign or malignant neoplasm affecting the thyroid gland. "In this study, we explored that NRXN2 was related to the formation of thyroid tumors and confirmed our hypothesis through a series of experiments." (PMID 34777568, 2021).
cancer (5 papers, 2011 to 2024). A tumor composed of atypical neoplastic, often pleomorphic cells that invade other tissues. "The functions of two further genes mutated in all 4 LTTs, namely NRXN2 (allelic frequencies 0.31–0.42) and FAM205A (allelic frequencies 0.28–0.85), are entirely unexplored in the context of cancer and chemoresistance." (PMID 31597922, 2019). "Our findings imply that NRXN2 plays essentially in some carcinomas." (PMID 34777568, 2021). "Nevertheless, it is yet elusive towards the roles of NRXN2 in the development of carcinoma." (PMID 34777568, 2021). "NRXN2 may participate in the tumorigenesis and development of cancer through these pathways, but there are few reports on the molecular function and potential mechanism of NRXN2 in cancer." (PMID 34777568, 2021). "One study reported that NRXN2 negatively regulated the activity of nuclear factor erythroid 2-related factor 2 (NRF2) and participates in the emergence and progression of multiple diseases, like carcinoma, metabolism, and neurodegenerative diseases." (PMID 34777568, 2021). "The roles of NRXN2 in cancer development have not yet been elucidated." (PMID 33101383, 2020).
tumor (3 papers, 2020 to 2024). "We believed that NRXN2 inhibited tumor progression by exerting proliferation and metastasis inhibitory effects in THCA." (PMID 34777568, 2021). "Collectively, our study demonstrated that, for the first time, NRXN2 behaved as an inhibitor of neoplasm and a promising biomarker in THCA." (PMID 34777568, 2021). "Our data showed that NRXN2 expression in primary neoplasm tissues was significantly lower relative to that in normal tissues." (PMID 34777568, 2021). "The downregulated NRXN2 was considered as tumor suppressors." (PMID 33101383, 2020).
neurological diseases (2 papers, 2020 to 2022). "NRXN2 belongs to the neurexin family, a group of synaptic cell adhesion molecules that play key roles in regulating synaptic functions and transsynaptic signaling (Südhof, 2017); it has also been proposed as a CSF biomarker candidate for several neurological disorders." (PMID 35602555, 2022).
brain diseases (1 paper, 2021). "As a protein related to nerve cells, NRXN2 is related to many brain diseases." (PMID 34777568, 2021).
infection (1 paper, 2023). The state of being infected such as from the introduction of a foreign agent such as serum, vaccine, antigenic substance or organism. "We found three genes that were commonly activated with infection with SCV2 at both 12 and 24 hpi (DUSP1, HES1, KLF2) and some non-congruent genes at 12 hpi (CCL5, ZBP1, NRXN2, STAB1, SLC25A47, CXCL11) and 24 hpi (FOXA2, RHOB)." (PMID 37504520, 2023).
psychiatric disorder (1 paper, 2015). A disorder characterized by behavioral and/or psychological abnormalities, often accompanied by physical symptoms. "This notwithstanding, our current data in Nrxn2α and Nrxn2 KO agree with many studies that reported dysfunction of NMDAR alters synaptic plasticity, and is associated with psychiatric disorders." (PMID 25745399, 2015).
NRXN2 also shares sentences with these, for which no sentence is quoted: neurodevelopmental disorder (3 papers); Intellectual disability (2); autoimmune disease (1); developmental delay (1); Epileptic encephalopathy (1); glioblastoma (1); hyperuricemia (1); mastitis (1); movement disorder (1); nephrolithiasis (1); neurodegenerative disease (1); Neurodevelopmental delay (1); pilocytic astrocytoma (1); thyroid cancer (1); Visual impairment (1).